IGF1 (insulin like growth factor 1)
Diseases named in the same sentence as IGF1 in open-access papers (continued):
Sharing a sentence is not in itself a finding about the gene and the disease.
acromegaly (continued). "The criteria for acromegaly diagnosis were GH level in 6 studies, GH and IGF-1 level in 13 studies, and IGF-1 level in 2 studies, and the criterion was not available in 2 studies." (PMID 38279102, 2024). "Hypersecretion of GH leads to excess insulin-like growth factor-1 (IGF-1) and results in acromegaly in adults and gigantism in children and adolescents." (PMID 39224564, 2024). "Achieving biochemical remission is one of the therapeutic goals for patients with acromegaly, and guidelines recommend maintaining serum IGF-1 within the sex- and age-specific normal ranges." (PMID 38370349, 2024). "In the case of acromegaly, different biological references were utilized, such as IGF-1, urinary cortisol, or GH levels." (PMID 39600946, 2024). "The primary goal of acromegaly treatment is to normalise GH and IGF-1 secretion and to remove or significantly reduce the mass of the pituitary tumour." (PMID 39598257, 2024). "In real-life settings, PAS-LAR significantly decreases symptoms, IGF-1 levels, and the size of adenoma in patients with acromegaly resistant to SRLs." (PMID 38244140, 2024). "While glucose and lipid abnormalities, as well as metabolic disorders, are frequently observed in patients with acromegaly, most cases can be effectively managed by normalizing IGF-1 levels." (PMID 38370349, 2024). "Because of their stability and low diurnal variation compared to GH, IGF-1 and IGFBP-3 levels are used to screen for GH secretory disorders, including gigantism, acromegaly, and GH deficiency, and to monitor GH treatment for short stature." (PMID 39403490, 2024). "Several case series reported that somatostatin receptor ligands reduced IGF-1 levels in acromegaly patients." (PMID 39104813, 2024). "The probability of uncontrolled acromegaly was also lower in those with IGF-1 levels 300–500 μg/L (ES = 0.37, 95% CI: 0.32–0.43), while it was significantly increased in those with IGF-1 values ≥700 μg/L at baseline (ES = 0.58, 95% CI: 0.53–0.64)." (PMID 38197875, 2024). "Acromegaly is described by surplus growth hormone with resultant elevated IGF-1 levels commonly from pituitary adenoma origin." (PMID 39595124, 2024). "Without effective biochemical control, indicated by normalized IGF-1 levels, patients with acromegaly face a range of disease-related comorbidities, with cardiovascular disease and malignancy being the main contributors of increased mortality." (PMID 39201352, 2024). "Presumably, in patients with acromegaly, the pathogenesis of goiter is attributed to an increased level of insulin-like growth factor 1 (IGF-1), which binds to its specific receptor, expressed in thyrocytes." (PMID 38455769, 2024). "The use of estrogen to treat acromegaly by decreasing liver IGF-1 production can date back to 1930s–1940s, although the underlined mechanism has not been fully understood." (PMID 39224564, 2024). "Biochemical evaluation, including insulin-like growth factor type 1 (IGF-1) measurement and oral glucose loading with growth hormone (GH) measurement confirmed excess GH production and a diagnosis of acromegaly." (PMID 38633358, 2024). "Acromegaly is a rare endocrine disorder characterized by increased growth hormone (GH) production, which leads to elevated insulin-like growth factor 1 (IGF-1) levels." (PMID 39201352, 2024). "In contrast, acromegaly is characterized by the increased secretion of growth hormone (GH) and, consequently, insulin-like growth factor-1 (IGF-1), which serves as a peripheral mediator of GH action." (PMID 39735646, 2024). "IGF-1 is an excellent disease marker and its normalization corresponds with the improvement of other metabolic and mortality-related indicators in acromegaly." (PMID 38279102, 2024). "The biochemical diagnosis of acromegaly is traditionally based on over-secreted GH and IGF-1 levels." (PMID 37584889, 2024). "In this article, we try to understand the effects of acromegaly on glucose homeostasis and the relationship between GH, IGF-1, and insulin signaling." (PMID 39119396, 2024).
acromegaly (continued). "Failure to suppress GH during OGTT is the cornerstone in the diagnosis of acromegaly in patients with increased IGF-1 levels." (PMID 37344722, 2024). "In summary, the patient with acromegaly was able to discontinue hypoglycemic medications and achieved satisfactory glycemic control after serum GH and IGF-1 levels normalized following secondary surgery and radiation therapy." (PMID 39331882, 2024). "Acromegaly is a slowly progressive disease characterized by increased release of growth hormone (GH) and, consequently, insulin-like growth factor I (IGF1), which is typically induced by a GH-secreting pituitary tumour." (PMID 38847918, 2024). "The studies included in our review predominantly utilized both IGF-1 and GH levels for diagnosing and assessing remission in acromegaly." (PMID 38279102, 2024). "Pasireotide is an effective treatment for both Cushing’s disease (CD) and acromegaly due to its ability to suppress adrenocorticotropic hormone and growth hormone, and to normalize insulin-like growth factor-1 levels, resulting in tumor shrinkage." (PMID 39735646, 2024). "This suggests that controlling IGF-1 levels within the standard range can decrease the incidence of NAFLD in individuals diagnosed with acromegaly." (PMID 38370349, 2024). "In patients with a clinical suspicion of acromegaly and elevated IGF-1 levels, the investigation of GH suppression during an oral glucose tolerance test (OGTT) is recommended as a confirmatory test." (PMID 37344722, 2024). "The aim of the presented study was to determine SCL, OPG, and RANK-L concentrations in patients with acromegaly with regard to the disease activity and to evaluate the association between sclerostin concentrations and OPG/RANK-L system, GH, IGF-1, and BMD." (PMID 39741885, 2024). "While earlier studies focused more on GH levels, IGF-1 measurement is a crucial part of the contemporary biochemical evaluation of acromegaly." (PMID 38279102, 2024). "Our meta-analysis provides a comprehensive evaluation of the complex relationship between IGF-1 levels and HF by examining data from the general population, HF patients, and individuals with treatment-naïve acromegaly." (PMID 39544311, 2024). "Based on these results, it is recommended that cardiac function be closely monitored in patients with reduced IGF-1 levels and in those with acromegaly." (PMID 39544311, 2024). "The primary goal of acromegaly treatment is the GH and IGF-1 levels normalization, which leads to disease control, improving life expectancy and reducing comorbidities." (PMID 38362280, 2024). "Acromegaly (AC) is a rare chronic endocrine condition involving structural and functional cardiovascular abnormalities due to abnormal growth hormone (GH) and insulin-like growth factor 1 (IGF−1) levels." (PMID 38256528, 2024). "The experts agreed on a holistic management approach to acromegaly, considering IGF-1 levels (with more stringent targets than in the past, at least in some categories of patients), tumor mass, complications, symptoms, and the patient’s QoL." (PMID 38809458, 2024). "A total of 1546 patients with acromegaly and treated with pegvisomant, with available information on baseline IGF-1 level, were included." (PMID 38197875, 2024). "Male patients with higher IGF-1 values have thicker temporal and masseter muscles, suggesting that sex and IGF-1 have a significant impact on muscle mass in acromegaly." (PMID 38967765, 2024). "In most cases, acromegaly occurs as a consequence of a growth hormone (GH)-secreting pituitary tumor that increases GH and insulin-like growth factor 1 (IGF-1) secretion." (PMID 38197875, 2024). "The 2020 Chinese expert consensus on acromegaly states that its qualitative diagnosis depends on measuring serum GH and IGF-1 levels and conducting an OGTT GH suppression test." (PMID 39331882, 2024). "Due to the nature of the claims data, we were unable to analyze how much higher IGF-1 levels were in the acromegaly group compared to the control group." (PMID 39220366, 2024).
acromegaly (continued). "International research, including studies involving patients with acromegaly from multiple countries, also demonstrated an increased incidence of HF, which correlated with IGF-1 levels." (PMID 39544311, 2024). "IGF-1 is also an indicator of acromegaly activity; its serum level, in correlation with GH level is useful in monitoring disease progression." (PMID 38668933, 2024). "In acromegaly, excessive secretion of GH stimulates hepatic IGF-1 production, and IGF-1 affects various tissues to result in various phenotypes of acromegaly." (PMID 39220366, 2024). "In conclusion, based on the recent assumption that both TMT and MMT are reliable measures of skeletal muscle mass, we demonstrated that sex and IGF-1 xULN values are the main determinants of muscle thickness in patients with acromegaly." (PMID 38967765, 2024). "The measurement of serum IGF-1 levels is crucial in the diagnosis of acromegaly in patients with suspected disease based on clinical symptoms along with the oral glucose toleration test-induced GH suppression as a confirmation test." (PMID 38668933, 2024). "The clinical manifestations of these tumors can be significant, with somatotroph adenomas leading to acromegaly in adults and gigantism in children due to excess growth hormone (GH) and insulin-like growth factor 1 (IGF-1) production." (PMID 39596626, 2024). "Although it is difficult to design large-scale prospective studies for rare diseases such as acromegaly, further studies will be needed to demonstrate the role of IGF-1 in the pathogenesis of acromegaly-related bronchiectasis." (PMID 39220366, 2024). "Acromegaly, predominantly resulting from a pituitary adenoma, is marked by excessive secretion of growth hormone (GH) and insulin-like growth factor-1 (IGF-1)." (PMID 39331882, 2024). "The probability of acromegaly uncontrol was also lower for values 300–500 μg/L (ES = 0.37, 95% CI: 0.32–0.43), while it was higher for baseline IGF-1 values ≥700 μg/L (ES = 0.58, 95% CI: 0.53–0.64)." (PMID 38197875, 2024). "The results indicated, as expected, elevated levels of IGF-1 up to 550 ng/ml (normal range typically between 80–280 ng/ml), which is acknowledged as one of the most reliable tests for diagnosing acromegaly." (PMID 39399792, 2024). "The endocrinological monitoring of acromegaly patients involved the assessment of insulin like growth factor -1 and GH levels." (PMID 39816387, 2024). "Blood workup revealed hyperprolactinemia, with a level of 7,237 mIU/L (normal range: 85–323), acromegaly with an IGF-1 level of 450 ug/L (normal range: 88–210), and a positive GH suppression test." (PMID 38654814, 2024). "In the partially cured group at the last follow-up, 2/8 (25%) patients showed active acromegaly (IGF-1 SDS + 2.75 and + 3.62; GH nadir 0.6 and 0.5 μg/l, respectively)." (PMID 38502285, 2024). "It is recommended that echocardiography be routinely conducted for patients with reduced IGF-1 levels and those with acromegaly to assess for any structural and functional cardiac impairments." (PMID 39544311, 2024). "This meta-analysis aims to elucidate the dual perspectives of IGF-1 levels in the general population, HF patients, and individuals with treatment-naïve acromegaly, highlighting IGF-1 as a biomarker and potential therapeutic target in HF management." (PMID 39544311, 2024). "The diagnosis of acromegaly was established by observing the distinct clinical manifestations of excessive growth hormone secretion, along with the elevated levels of serum IGF-1 and serum GH of greater than 1 ng/mL." (PMID 38455769, 2024). "Our results confirmed and for the first time quantified the central role of the baseline IGF-1 values on the probability of achieving a biochemical control of acromegaly during the treatment with pegvisomant." (PMID 38197875, 2024). "The patient’s serum GH and IGF-1 levels were significantly elevated, and the clinical manifestations were consistent with acromegaly." (PMID 39331882, 2024).
acromegaly (continued). "Hypersecretion of GH and IGF-1 in acromegaly increases cardiovascular complications, morbidity, and mortality due to coagulation activation and fibrinolytic system impairments." (PMID 37584889, 2024). "Studies exploring the roles of the GH/IGF-1 axis in TC have primarily focused on individuals with acromegaly, who typically exhibit elevated GH and IGF-1 levels." (PMID 39104813, 2024). "Acromegaly is a rare and insidious hormonal disorder, characterized by excessive secretion of growth hormone (GH) and insulin-like growth factor-1 (IGF-1)." (PMID 38965637, 2024). "Acromegaly, characterized by excessive GH secretion and elevated IGF-1 levels, offers a unique context for examining the effects of high IGF-1 levels on HF risk." (PMID 39544311, 2024). "Acromegaly is most often the result of monoclonal expansion of GH-secreting cells within a pituitary adenoma, leading to chronic overproduction of GH and IGF-1." (PMID 39331882, 2024). "Hormone values for GH and IGF-1 can only be reported for patients with an acromegaly diagnosis in the SPR." (PMID 37851314, 2024). "Diagnosis of acromegaly is performed by measuring GH and IGF-1; besides, imaging studies like brain computed tomography (CT) scan and magnetic resonance tomography imaging (MRI) were used to show the size and extension of pituitary adenomas." (PMID 37584889, 2024). "Acromegaly is a disease characterized by excessive secretion of growth hormone (GH) and insulin-like growth factor-1 (IGF-1)." (PMID 38709454, 2024). "Although the effects of serum GH/IGF-1 levels on hepatic steatosis are known, there is limited data on hepatic steatosis and hepatic fibrosis in patients with newly diagnosed acromegaly." (PMID 38709454, 2024). "Hormonal control results in the reduction of symptoms and mortality rates; hence, the acromegaly treatment aims to normalize IGF-1 levels, according to the 11th Acromegaly Consensus Conference." (PMID 37364152, 2023). "Bovine GH transgenic (bGH) mice overexpress GH and possess increased levels of IGF-1, resulting in increased body mass and length and lean body composition, similar to acromegaly." (PMID 36837810, 2023). "The overall disease-controlled rate of acromegaly in our cohort was 45.9% when setting GH < 1.0 ng/ml and IGF-1 ULN ≤ 1.0 as the cutoff, which was relatively low among recent large-scale studies (46–75%)." (PMID 37442901, 2023). "After transsphenoidal resection she had declining, but persistently elevated, insulin-like growth factor 1 (IGF-1), raising concern for persistent acromegaly." (PMID 38192880, 2023). "Excessive concentrations of GH and IGF-1 in patients with acromegaly stimulate the synthesis of 1,25-dihydroxyvitamin D (1,25(OH)2D), which deregulates the calcium and phosphate metabolism leading to hypercalcemia." (PMID 37373574, 2023). "Patients with pituitary microadenoma or macroadenoma and elevated insulin-like growth factor-1 should be closely monitored for signs/symptoms of acromegaly and hypopituitarism." (PMID 37543629, 2023). "Our findings show the importance of IGF-1 in pathogenesis of left ventricle hypertrophy in acromegaly." (PMID 36309947, 2023). "Global LV-LS was found to be reduced in 48% of patients with active acromegaly and systolic blood pressure (BP), N-terminal (NT) prohormone of brain natriuretic peptid (BNP), IGF-1, LA diastolic diameter, LV mass index were associated with global LV-LS." (PMID 37959322, 2023). "Lastly, the modulation that estrogens/SERMs can induce on local GH and/or IGF1 excess or activity can be of interest in some types of high-impact cancers, studied in patients with acromegaly as a model and translated to the general population." (PMID 37373068, 2023). "Men had significantly higher biochemical activity of acromegaly compared to women measured by IGF-1 concentration: 3.9 (IQR 3.0-4.7) x ULN vs. 2.8 (IQR 2.1-3.3) x ULN, p=0.027." (PMID 37223021, 2023).
acromegaly (continued). "During pregnancy IGF-1 determinations were in the reference range, however, two months after labor, acromegaly recurred (IGF-1 1.5 times the ULRR), while breastfeeding." (PMID 36973824, 2023). "Octreotide capsules (Mycapssa®) have established clinical efficacy in maintaining normalization of GH and IGF-1 levels equivalent to those of parenteral octreotide injections in trials of both healthy patients and those with diagnosed acromegaly." (PMID 37755395, 2023). "The random GH levels (39.2 ng/mL ± 98.05 ng/mL) and IGF-1 levels (959 ng/mL ± 273.85 ng/mL) in active male acromegaly patients were higher than in the normal population." (PMID 37886642, 2023). "Screening for acromegaly is primarily accomplished through the biochemical evaluation of IGF-1 due to the highly variable daily fluctuations of GH concentration related to temporal factors, exercise, and sleep patterns." (PMID 37755395, 2023). "Normalization of both IGF-1 and GH is the primary aim of therapies targeted to treat acromegaly due to the well-supported improvement in patient outcomes and decreased mortality when normalization of hormone levels is achieved." (PMID 37755395, 2023). "Poor glycemic control has challenged acromegaly diagnosis due to low/normal IGF-1 level in 2 case studies; similarly to “wild-type” T2DM, IGF-1 also increases post insulin-treatment in secondary DM." (PMID 36882643, 2023). "The level of IGF-1 was elevated in 11/94 patients, further acromegaly was confirmed in 3/94 patients (3.2%)." (PMID 38796756, 2023). "In summary, GH and IGF-1 directly affect myocardial mechanics in acromegaly,with concentric hypertrophy of both ventricles, more prominently the left,resulting in diastolic dysfunction and rarely systolic dysfunction." (PMID 39076279, 2023). "Risks of acromegaly with uncontrolled GH and IGF-1 levels include tumor mass effect, cardiovascular complications, and respiratory complications, all contributing to an elevated mortality rate in these patients." (PMID 37755395, 2023). "In acromegaly caused by GH-secreting pituitary adenoma, serum concentrations of IGF-1 and the PTH-dependent production of IGF-1 by osteoblasts are increased, with a consequent enhancement of bone remodeling." (PMID 37266131, 2023). "The key predictor of the case-by-case mortality rate in acromegaly is the post-operative GH levels, with controlled GH/IGF-1 levels increasing life expectancy to that of the age-matched controls." (PMID 37755395, 2023). "Newly diagnosed acromegaly patients were presented with the highest IGF-1 and GH levels compared to uAP and cAP (P < 0.001)." (PMID 36309947, 2023). "Acromegaly is a disorder characterized by overproduction of growth hormone (GH) and the resulting elevation of insulin-like growth factor (IGF-1)." (PMID 36508085, 2023). "Acromegaly is a disease characterized by excessive growth hormone (GH) secretion and consequently increased secretion of insulin-like growth hormone (IGF-1), usually in a growth hormone-producing pituitary tumor." (PMID 37373801, 2023). "Recovery from acromegaly had a direct effect on recovery of testosterone levels for suppression of testosterone production due to the effect of excess GH and IGF-1 was removed." (PMID 37886642, 2023). "Opportunities exist indeveloping a new drug to effectively balance GH/IGF-1 levels, as this will be ofgreat benefit in the management of HF subjects with acromegaly." (PMID 39076279, 2023). "If a patient presents with an ambiguous IGF-1 level, but physiologic or metabolic clinical findings still suggest acromegaly, a GH suppression test can be performed to measure GH levels before and two hours after a 75 g glucose load is orally administered." (PMID 37755395, 2023). "Atherosclerosis in acromegaly is controversial since there is notmuch evidence on the effect of IGF-1 on forming atheromas." (PMID 39076279, 2023).